CCND1 (cyclin D1)
Diseases named in the same sentence as CCND1 in open-access papers (continued):
Sharing a sentence is not in itself a finding about the gene and the disease.
tumor (continued). "Western blot analyses from infigratinib‐resistant tumour collected at different passages indicated an elevation in cell cycle proteins such as cyclin E2, cyclin B1, Cdc25C, p‐Cdc2, cyclin D1, Rb and p‐Rb." (PMID 33179425, 2021). "Upregulated miR-449a suppresses CRC tumorigenesis including cell proliferation, migration, invasion, and tumor formation by silencing the expression of target genes Cyclin D1 and LEF-1 at the translational level." (PMID 34737955, 2021). "Cyclin D1 overexpression is a key determinant of the reciprocal interaction between cancer cells and the stroma, resulting in a “tumor-promoting” effect." (PMID 34903946, 2021). "Western blots showed that ABP treatment reduced the expression levels of β-catenin, Cyclin D1, and c-Myc in tumor tissue samples." (PMID 34552494, 2021). "Collectively, these results indicated that licorice is likely to induce tumor cells arrested at G0/G1 growth phase by down-regulating CDK4-Cyclin D1 complex." (PMID 34641869, 2021). "HDAC4 regulates the expression of E-cadherin, N-cadherin, Snail and Slug, and cyclin D1 to promote tumor growth and metastasis in NPC." (PMID 33542203, 2021). "Loss‐of‐function studies uncovered that circ‐CCND1 suppressed LSCC cell proliferation and tumour growth." (PMID 34672397, 2021). "The COV of Ki-67 labeling index ranged from 18.2% in patient 51 to 40.3% in patient 26 with Cyclin D1 labeling index also showed a wide dispersion within the same tumor with COVs from one patient to another ranging from 14% to 38.5%." (PMID 34394279, 2021). "Clear evidence does exist that tumor cells exposed to CCND1/CDK4 and CDK6 complex inhibitor increase their sensitivity to IR thanks to the induction of sustained DNA double-strand breaks (DSB)." (PMID 34445095, 2021). "Rescue experiments indicated that LINC01503 inhibition suppressed the invasion and proliferative ability of the tumor cells, a phenomenon that was reversed following miR-615-3p inhibition or CCND1 overexpression." (PMID 34149919, 2021). "In vivo, after administration of AUR + radiotherapy significant regression in tumor size, down regulation of Cyclin D1 and CD44, involvement of PI3K-AKT-mTORC signaling pathway and Caspase-3 was observed." (PMID 34239445, 2021). "This surprised us because CREPT was shown to elevate CCND1 and c-Myc expression significantly through Wnt signaling in tumor cells." (PMID 33431892, 2021). "In PC, CCND1 was up-regulated in tumor tissues, which was significantly correlated with the degree of differentiation and poor prognosis." (PMID 33996561, 2021). "Fulvestrant in combination with palbociclib showed a partial response to the relevant patient’s tumor harboring the ESR1 mutation, and CCND1 amplification was found in the PDX model." (PMID 33407601, 2021). "The cancer cell survival suppressive effect of dipyridamole was paralleled by a reduction of the HMGB1/RAGE axis, and proliferation- and migration-related β-catenin, YAP1, Runx2, TGFβ1/Smad, and cyclin D1 in in vitro and in vivo tumor growth models." (PMID 33669632, 2021). "Aberrant Wnt/β-catenin signaling is involved in the progression of different tumor types through modulation of downstream targets, such as c-myc, cyclin D1, and GSK-3β." (PMID 34090445, 2021). "As a tumor suppressor, GSK3β can phosphorylate and inactivate several oncogenes, including β-catenin, c-Myc, and cyclin D1 – ultimately inhibiting tumor cell proliferation." (PMID 34023818, 2021). "Recent work from our lab determined that the basolateral complexes promote tumor progression via increased expression of Cyclin D1, Snail, and Myc and also increased Src family kinase activity." (PMID 33525380, 2021). "Compared to sh‐NC + oe‐NC, transfection of sh‐E2F1 + oe‐NC in the cells reduced the expression of E2F1 and CCND1 in the tumor tissues." (PMID 34758200, 2021). "Metformin decreased the expression of cyclin D1 and PCNA which are associated with cell cycle and tumor induction, respectively." (PMID 33893356, 2021).
tumor (continued). "Cyclin D1 plays a multifaceted role in tumor progression, while its major function is to transfer G1 phrase of cell cycle to S phrase, which induces DNA synthesis and promotes cell proliferation." (PMID 34699325, 2021). "We also performed immunohistochemistry (IHC) to evaluate Cyclin D1 protein levels in NSCLC patient tissue samples, and found that the majority of the tumor cells stained positively for Cyclin D1." (PMID 33833996, 2021). "In particular, sample 56 showed very few copies of E7 integration and displayed an oncogenic CCND1 mutation in WES, which is more likely to be the oncogenic driver in this tumor sample with HPV as a bystander infection." (PMID 34944992, 2021). "Although, at mRNA level, CCND1 expression wassignificantly lower in tumor samples (P<0.001), SOX2, BRAF,TNFA, and VEGF expression was increased in malignant tissuescompared with normal adjacent samples (P<0.05)." (PMID 34308569, 2021). "We also demonstrated that the expression levels of cyclin-D1 which are well known for playing a key role in tumour growth and proliferation were significantly reduced by rivoceranib treatment in a dose-dependent manner in both cell lines." (PMID 34702279, 2021). "In the present study, we evaluated the anti-tumor effects of candesartan on CRC cells through investigating expression of cyclin D1 and MMPs." (PMID 34121975, 2021). "We further verified the expression levels of YTHDF2, GSK3β, β‐catenin and Cyclin D1 in 150 pairs of tumour and ANTs." (PMID 34709763, 2021). "Cyclin D1, known as an essential cell cycle regulator, has also been proved participated in tumor cellular migration and invasion." (PMID 33833997, 2021). "Many studies have found that Cyclin D1 promotes the cell cycle transition from G1 to S phase, while downregulation of Cyclin D1 can induce G2/M-phase arrest in tumor cells." (PMID 34224316, 2021). "Since CDK4 is activated by CCND1, recent studies have shown that it is also overexpressed in several cancer types and shares similar oncogenic characteristic with CCND1 in tumor tissues." (PMID 34063946, 2021). "In our series, the median Ki-67 and Cyclin D1 values were 32.65% and 32.12% respectively, which means that the 51 tumors studied had a great proliferative activity reflecting the tumor aggressiveness of IDC." (PMID 34394279, 2021). "As compared to the control group, expression of cyclin D1, Ki-67 protein, and proliferating cell nuclear antigen was decreased in tumor tissues in the group treated with metformin and DCA was decreased." (PMID 34576192, 2021). "Consistently, CASC2 overexpression significantly decreased and CASC2 silencing increased proliferating markers cyclin D1 and ki67 in tumor tissues." (PMID 35145900, 2021). "As observed in ELF3 knockdown or ANF treatment in vitro experiments in A549 and H1975 cells, cyclin A2, cyclin B1, and cyclin D1 were reduced in xenograft tumor tissues treated with ANF/GEF combination." (PMID 34830169, 2021). "Immunohistochemistry (IHC) of isolated tumor tissues showed that the expression of Ki67 and the positive rate of cyclin D1 were significantly higher in tumor tissues of the P+ group." (PMID 34660289, 2021). "Ccne1, Ccnd1 and Ccna2 were significantly induced in tumours compared to surrounding liver tissues of Ccne1f/f and Cdk2f/f animals." (PMID 34830835, 2021). "To further understand this, we performed a detailed analysis of the SHANK2 and Cyclin D1 amplification status in COSMIC tumor samples." (PMID 32661924, 2021). "The expressions of β-catenin and its target, c-Myc and cyclin D1, in tumor tissues were significantly reduced in mice treated with STA9090 than those in the Huh7-DDX5-KD group." (PMID 33764710, 2021). "Although the overexpression of CDK4 and cyclin D1 is also observed in EMPD tumor cells, the correlation between their expression and patients’ prognosis has not been elucidated." (PMID 34395284, 2021).
tumor (continued). "It is well known that Cyclin D1, c-Myc and Cox2 can promote the proliferation of tumor cells while PTEN can suppress the PI3K/AKT/mTOR signaling." (PMID 34026596, 2021). "This novel miR200b/QKI/CCND1 axis played a role in tumor angiogenesis via the CCND1-mediated endothelial cell cycle progression." (PMID 34439268, 2021). "CCND1 is a crucial cell cycle regulatory protein whose expression and cellular localization is frequently transformed in tumor cells, and it is capable of inducing cell proliferation, invasion, and transformation in human malignancies." (PMID 34758200, 2021). "PRMT5 epigenetically suppresses the expression of several tumor suppressor miRNAs, such as miR33b, miR96, and miR503, which bind to and target the mRNA corresponding to Cyclin D1 and/or c-Myc." (PMID 34006904, 2021). "MIA PaCa-2 tumor-derived 3D cultured in the presence of Wnt3A showed a strong signal of active β-catenin concomitant to an increase of nuclear Cyclin D1 localization and accumulation." (PMID 34203710, 2021). "Regarding CCND1, we first analyzed the potential correlation between CCND1 DNA methylation and mRNA expression in tumor tissue." (PMID 34933671, 2021). "CCND1/cyclin D1 have also been proposed as a candidate therapeutic target, because their transcription depends on several upstream pathways essential for tumor development." (PMID 33804108, 2021). "The analysis including the cases of tumor in situ revealed that the overexpression of both CDK4 and cyclin D1 in EMPD tumor cells was significantly correlated with worse DSS (HR: 4.76, p = 0.033)." (PMID 34395284, 2021). "N6L treatment inhibited the growth of MIA PaCa-2 tumor-derived 3D culture and decreased active β-catenin and nuclear Cyclin D1 signals." (PMID 34203710, 2021). "First, the RT‐qPCR results showed that miR‐107 mimic reduced the expression of CCND1 in the tumor tissues." (PMID 34758200, 2021). "Although CDK4/6 can bind with cyclin D1, resulting in Rb hyperphosphorylation, palbociclib can block Rb phosphorylation and prevent E2F1 release by separating CDK4/6–cyclin D1 complexes, resulting in G1 phase arrest and inhibit tumor growth." (PMID 34395246, 2021). "Our work is essentially a quantitative approach demonstrating tumour heterogeneity by the markers Ki-67 and Cyclin D1 expression." (PMID 34394279, 2021). "Stress-induced tumor cell proliferation was at least partly due to the downregulation of miR-346, miR-493 and four other miRNAs and upregulation of CCND1 in tumor cells." (PMID 34689156, 2021). "It has been reported that miR-34a influenced tumour biological activities by targeting several genes or signal pathways, such as CCND1 in EC, PDGFR in GC, HMGB1 in CRC, and XIST in PC." (PMID 33446130, 2021). "CCND1 amplification was associated with the exclusion of cytotoxic cells, T CD8+ and B+ T cells and dendritic cells (DCs) in the tumor microenvironment (TME)." (PMID 34445095, 2021). "Gene amplifications of CCND1, CDK12, CCNE1, and ERBB2 were identified in patients with low tumor mutational burden." (PMID 34068652, 2021). "In summary, this study evidenced that licorice induced G0/G1 phase cell cycle arrest by down-regulating CDK4-Cyclin D1 complex on tumor cells." (PMID 34641869, 2021). "Cyclin D1 knockout delayed tumor formation and reduced tumor size and multiplicity upon TPA/DMBA treatment." (PMID 34553848, 2021). "Loss of APC or GSK3 therefore activates Wnt target genes, such as MYC (c-Myc) and CCND1 (cyclin D1), and promotes tumor growth, as described in greater detail below." (PMID 33525562, 2021). "Another crucial protein, cyclin D1, a downstream protein of c-Myc to drive cell G1-to-S phase transition, plays an important role in normal cell proliferation and aberrant tumor cell diffusion." (PMID 34434893, 2021).
tumor (continued). "The skin metastasis sample showed a very similar pattern of alterations in driver genes as compared with the treated tumor, including the PIK3CA hotspot mutation, the amplifications in CCND1, EGFR, and FGFR3, and the deletions in CDK1B, CDKN2A, and CDKN2B." (PMID 34680239, 2021). "Up-regulation of miR-15a/16-1, regulated by CXCR4, results in the repression of BCL-2 and cyclin D1. miR-15a/16-1 increases apoptosis and reduces the proliferation and survival of tumor cells." (PMID 33718173, 2021). "Cyclin D1 is frequently deregulated in cancer, and it is a biomarker of tumor phenotype and disease progression." (PMID 34717617, 2021). "MiR-15a-5p is a tumor suppressor, promoting apoptosis and inhibiting cell proliferation by targeting multiple oncogenes, including Bcl-2, Mcl1, CcnD1, and Wnt3A33,34." (PMID 33456354, 2021). "As a downstream protein of the MAPK signaling pathway, EGR1 can promote transcriptional activation of cyclin D1 in many tumor types and maintain the mitosis of tumor cells." (PMID 33842351, 2021). "Tumor-specific glucose fermentation enhances the recruitment of CBP/p300 to CCND1 gene to promote tumor cell proliferation." (PMID 34201346, 2021). "To date, our results suggest that IRS-4 behaves like cyclin D1 and Ki-67, both of which are robust markers of tumor proliferation." (PMID 34071030, 2021). "Western blotting indicated the augmentation of cleaved PARP and cyclin B1 and downregulation of cyclin D1, suggesting that heptelidic acid exerted tumor-suppressive functions by mediating the dysregulation of the cell cycle and induction of apoptosis." (PMID 34040123, 2021). "Pre-treatment with PD synchronized the tumour cell cycle through the CDK4/6-cyclin D1-RB-E2F pathway, which increased the antitumour effect of CDDP." (PMID 33061853, 2020). "The increased expression of Cyclin D1 contributes significantly to tumor development and malignant transformation." (PMID 32382534, 2020). "Analysis of expression changes between tumor and normal tissues revealed that a considerable fraction of tumors downregulates CCND1 expression." (PMID 32224897, 2020). "Higher expression of Cyclin D1 was strongly correlated with advanced tumor stage and positive lymph node metastasis in HNSCC." (PMID 33049713, 2020). "In some studies, Cyclin D1 expression was correlated with poor prognosis in the tumor cells, and it is overexpression has reflected the aggressiveness of cancer." (PMID 32552908, 2020). "FOXM1 contributes to multiple cancers by promoting cellular proliferation and tumor initiation via β-catenin and cyclin D1." (PMID 32391055, 2020). "It has been shown that CCND1 promotes tumor progression mainly by shortening G1 phase, resulting in an increase in the number of cells progressing through G1 phase." (PMID 31982864, 2020). "The higher expression of Cyclin D1 in metastatic tumours can be explained by the fact that alterations are related to strong proliferative activity and invasive mode of inclination of the lesions." (PMID 31983161, 2020). "The CCND1 is critical for tumor cell cycle, while laminins are essential for the formation and function of the basement membrane and regulation of cell migration and mechanical signal transduction." (PMID 32545325, 2020). "In tumor tissue of animals treated with fruti we observed a reduction of Cyclin D1, Bcl-2 and Rela (a protein from NF-κB pathway) expression and of p-NF-κB/NF-κB protein ratio, in line with our observations from in vitro experiments." (PMID 33020521, 2020). "When CCND1 amplification is included in the interpretation of cancer prognosis, issues such as tumor type, standardization of detection, and accompanying gene mutation status should be fully considered." (PMID 32903763, 2020). "Through univariate and multivariate analysis, we further revealed that tumor stage, lymph node metastasis, and cyclin D1 positive expression were highly correlated with the prognosis of NPC patients." (PMID 32697404, 2020).
tumor (continued). "Patients’ and PDX tumours both carried CCND1 amplification and a homozygous deletion of CDKN2A was identified in PDX." (PMID 32792481, 2020). "Previous reports demonstrate that cyclin D1 confers chemo- and radioresistance to several tumor cells." (PMID 32872659, 2020). "Enhances radiation-induced apoptosis by inhibiting STAT3; it also downregulates Mcl-1, cyclin D1 and survivin expression, overcomes resistance to radiation in cells and suppresses tumor growth in vivo." (PMID 32872659, 2020). "A previous PCa sequencing data of our institution showed CCND1 mRNA level was higher in adjacent normal tissue than tumor tissue (P < 0.001) which further confirmed the cytoplasmic CCND1 protein expression level results of IHC data in this study." (PMID 32566661, 2020). "Our study is a preliminary investigation mainly focused on the predictive function of CCND1 amplification in the tumor microenvironment (TME) in the aspect of genome and transcriptome." (PMID 32903763, 2020). "This work highlights DHX9’s ability to form alternative complexes with either EWS-FLI1 or pncCCND1_B/Sam68 in modulating CCND1 expression in Ewing sarcoma cells, exhibiting both oncogenic and tumor suppressive functions." (PMID 33437516, 2020). "Animal studies also demonstrated that knockdown of Cdk5 inhibited tumor growth, while levels of cyclin D1 and c-Myc expression were markedly decreased in the Cdk5 knockdown group vs. control group." (PMID 33488528, 2020). "Cell cycle regulation for sure can contribute to cisplatin resistance, as demonstrated by the differential (over)expression of CCND1 (Cyclin D1) in platinum-resistant tumor samples." (PMID 32560427, 2020). "Diverse E3 ligases and DUBs are associated with Wnt signaling factors, resulting in upregulation or downregulation of Wnt target genes such as c-Myc and Cyclin D1, which are related to tumor growth." (PMID 32486158, 2020). "It is reported that rise of autophagy-dependent Cyclin D1 degradation using amiodarone and rapamycin, represses tumor growth in both the orthotopic liver tumor and subcutaneous tumor xenograft models." (PMID 33317149, 2020). "This enabled us to detect a novel circRNA, circEIF3M, which promotes tumor cell progression by acting as a sponge for the miR-33a, thereby relieving the microRNA repression of target gene cyclin D1 (CCND1)." (PMID 32652519, 2020). "Similar to ESCC cell cultures, the GSK3β inhibitors significantly reduced tumor cell proliferation (Ki-67-positive cells), pGSS641 level and cyclin D1 expression, while inducing apoptosis (TUNEL- and c-PARP-positive cells)." (PMID 32678196, 2020). "In PCa, the miR-15a/miR-16 cluster was found to suppress tumor invasion by suppressing the TGF-β signaling pathway to inhibit growth through CCND1 and WNT3A." (PMID 33614501, 2020). "The antiproliferative activity of β-caryophyllene in KB oral cancer cells was found to be also mediated by a reduced expression of PCNA (proliferating cell nuclear antigen) and cyclin D1, which are required for tumor cell growth and survival." (PMID 33081075, 2020). "Phosphorylated STAT3 increases tumor cell proliferation, migration, and invasion by increasing the expression of genes such as b-cell lymphoma 2 (Bcl2), cyclin D1, and c-myc." (PMID 32432040, 2020). "Further confirmation was obtained by the transcriptional analysis for the β-catenin targets c-MYC and Cyclin D1, involved in regulating tumor growth and cellular proliferation." (PMID 32481626, 2020). "Tremendous efforts have been made to inhibit tumor growth by targeting Cyclin D1-CDK 4/6 or its upstream pathways, with several successful drugs available in the clinic." (PMID 33139730, 2020).